MRPS12 (mitochondrial ribosomal protein S12)
Synonyms: RPMS12; RPSM12; RPS12; uS12m; MPR-S12; MT-RPS12
Tractability: Small molecule: a structure with a bound ligand is known. PROTAC: ubiquitination databases record sites on it; its protein half-life has been measured.
Gene: Protein-coding gene on chromosome 19 (38,930,923 to 38,933,183, forward strand). Ensembl gene ENSG00000128626.
Subcellular location: Mitochondrion
Pathways (Reactome):
Metabolism of proteins: Mitochondrial ribosome-associated quality control; Mitochondrial translation elongation; Mitochondrial translation initiation; Mitochondrial translation termination
Gene Ontology:
Molecular function: protein binding; RNA binding; structural constituent of ribosome
Biological process: mitochondrial translation; translation
Cellular component: mitochondrial small ribosomal subunit; mitochondrion; mitochondrial inner membrane; mitochondrial ribosome; ribosome; small ribosomal subunit
Genetic constraint (gnomAD): Loss-of-function variants: 9 observed, 9.88 expected, observed/expected ratio (o/e) 0.91, 90% interval 0.55 to 1.57. That is too few expected variants to judge how well the gene tolerates losing a copy. Missense variants: 200 observed, 198.55 expected, observed/expected ratio (o/e) 1.01, 90% interval 0.9 to 1.13. Synonymous variants: 84 observed, 85.62 expected, observed/expected ratio (o/e) 0.98, 90% interval 0.82 to 1.18.
Homologues: Orthologues: chimpanzee MRPS12 (99% identical), macaque MRPS12 (96% identical), guinea pig MRPS12 (89% identical), rat Mrps12 (87% identical), mouse Mrps12 (86% identical), rabbit MRPS12 (84% identical), dog MRPS12 (83% identical), pig MRPS12 (81% identical), tropical clawed frog mrps12 (68% identical), zebrafish mrps12 (62% identical), Drosophila melanogaster tko (53% identical), Caenorhabditis elegans mrps-12 (45% identical). Paralogues in human: RPS23 (30% identical).
Diseases named in the same sentence as MRPS12 in open-access papers:
MRPS12 is named in the same sentence as 18 diseases in open-access papers, as found by Europe PMC text mining. Sharing a sentence is not in itself a finding about the gene and the disease. The quoted sentences say what the papers report.
ovarian carcinoma (7 papers, 2021 to 2025). A malignant neoplasm originating from the surface ovarian epithelium. "Association with these pathways suggests that MRPS12 may be involved in limiting apoptosis in cancer cells, which may explain the increased tumour recurrence in breast and ovarian cancers." (PMID 39354291, 2024). "Likewise, in ovarian cancer, the expression of MRPS12 is also associated with recurrence and advanced disease stage." (PMID 39354291, 2024). "Another study found that the expression of MRPS12 is positively correlated with the infiltration of macrophages and neutrophils in ovarian cancer, and MRPS12 is a potential oncogene and a promising prognostic candidate in ovarian cancer." (PMID 37418282, 2023). "MRPS12 is a potential oncogene of ovarian cancer, while MRPL27 displays an adverse effect on the overall survival rate and disease-free survival rate of cholangiocarcinoma patients." (PMID 34868337, 2021). "MRPS12 is a potential oncogene for ovarian cancer, being a potential prognostic biomarker." (PMID 39478854, 2024). "Thus, MRPS12, the most stably expressed gene in “N”, is a potential prognostic candidate for ovarian cancer, while UXT the most unstably expressed gene in “N” is associated with advanced stages of gastric cancer." (PMID 34209090, 2021). "PKM2, MRPS12, NDUFC2, HPDL, MRPL14, COA6 and RNF144B were significantly upregulated in ovarian cancer tissues than in normal tissues (P < 0.05), while RPL23, FGFR1OP2, CAPN10, ALDH1L1 and ACSM1 were significantly down-regulated (P < 0.05)." (PMID 39478854, 2024). "Biomarkers such as RPL23, MRPS12, and ALDH1L1 have been used to predict the prognosis of ovarian cancer, but most studies focus on the prognostic role of a single biomarker." (PMID 39478854, 2024). "PKM2, MRPS12, NDUFC2, HPDL, MRPL14, COA6 and RNF144B were significantly upregulated in ovarian cancer, but the down-regulation of NDUFC2, HPDL, MRPL14, COA6 and RNF144B was associated with poor prognosis in patients with ovarian cancer." (PMID 39478854, 2024).
breast carcinoma (5 papers, 2019 to 2025). "In terms of therapeutics, MRPS12 has been associated with tamoxifen resistance in breast cancer, where combination therapies including tigecycline inhibited proliferation and enabled selective toxicity in cancer cells." (PMID 39354291, 2024). "To biologically validate these findings, we performed IHC assay to detect the expression of four proteins (PROM1, LAMB3, SLC6A4, and MRPS12) generated from those genes found to be differentially expressed in HIV-positive breast cancer samples." (PMID 33194615, 2020). "In contrast, SLC5A11, SLC6A4 and MRPS12 were the most downregulated in HIV-positive breast cancer with a long2foldchange of −6.7, 6.5 and −4.7, respectively." (PMID 33194615, 2020). "Higher expression of MRPS12 and NDUFS6 correlates with decreased metastasis-free survival in breast cancer." (PMID 40909564, 2025). "Collectively, signaling protein analysis revealed a highly activated pathway of post-translational modification and protein transport to the rough endoplasmic reticulum (via GFM, MRPS12, RPS21, and SRP9), suggested circuitry to predict breast cancer outcomes." (PMID 32252260, 2020). "The co-expression network revealed that ELAVL2, VIM, MRPS12, HSPE1, EZH2, HIST1H4B, and MRPL13 played a vital role in the progression of breast cancer, and we further selected important modules of target genes through MCODE." (PMID 30881302, 2019).
COVID-19 (2 papers, 2022 to 2023). A disease caused by infection with severe acute respiratory syndrome coronavirus 2. "Among the transcripts related to the term “mitochondrial gene expression,” polyribonucleotide nucleotidyltransferase 1(PNPT1) showed the highest upregulation in the COVID-19 cohort, followed by MRPL24 and MRPS12." (PMID 36443881, 2022).
breast tumours (1 paper, 2023). "Finally, we provide evidence that high expression of the OXPHOS-related genes NDUDS6 and MRPS12 in breast tumours is associated to poor prognosis in a large cohort of BC patients." (PMID 37452026, 2023). "Therefore, we analysed the expression of 6 genes from the OXPHOS signature (AIFM1, NDUFV1, NDUFAB1, NDUFA7, NDUFS6 and MRPS12) among the most enriched in metastatic samples, by RT-PCR in specimens of 503 breast tumours patients with a follow-up of 20 years." (PMID 37452026, 2023).
deafness (1 paper, 2023). An inherited or acquired condition characterized by the complete loss of the ability to hear from one or both ears. "Hence, the mapping of 11 potentially disruptive variants to the neighborhood of protein MRPS12/uS12m could be tentatively interpreted as further proof of the involvement of mito-ribosomal fidelity in the etiology of mt-rRNA-induced deafness." (PMID 37362424, 2023).
glioblastoma (1 paper, 2021). The most malignant astrocytic tumor (WHO grade IV). "Furthermore, some evidence suggests that several genes expressing MRPs including bS1m (MRPS28), uS2m (MRPS2), uL23m (MRPL23), uS12m (MRPS12), bL12m (MRPL12) and mS34 (MRPS34) may be potential biomarkers for the treatment of glioblastoma with Benzyl isothiocyanate (BITC)." (PMID 34071057, 2021).
hepatocellular carcinoma (1 paper, 2025). A malignant tumor that arises from hepatocytes. "MRPS12 is associated with the prognosis of HBV-related hepatocellular carcinoma and drives the malignant phenotype of hepatocellular carcinoma by regulating mitochondrial metabolism." (PMID 40371222, 2025).
ischemic stroke (1 paper, 2023). A stroke disorder caused by obstruction of blood flow to the brain, due to thrombotic (local blood clot formation) or embolic (due to a blood clot or other material traveling from another site) event. "Additionally, MRPS11 and MRPS12 could potentially serve as therapeutic targets for the treatment of ischemic stroke, as mitochondrial dysfunction has been implicated in stroke pathophysiology." (PMID 37418282, 2023). "MRPS11 and MRPS12 have the potential to serve as biomarkers for ischemic stroke diagnosis, either alone or in combination with other biomarkers." (PMID 37418282, 2023). "At last, PCR showed that MRPS11 and MRPS12 were significantly down-regulated in peripheral blood of patients with ischemic stroke." (PMID 37418282, 2023). "We found that both MRPS11 and MRPS12 were down-regulated in ischemic stroke patients in the GSE16561 and GSE58294 data sets (p < 0.001)." (PMID 37418282, 2023). "The present study identified MRPS11 and MRPS12 as robust markers in transcriptomic analysis of ischemic stroke." (PMID 37418282, 2023). "The results showed that compared with healthy controls, MRPS11 and MRPS12 were significantly down-regulated in peripheral blood of patients with ischemic stroke (**P < 0.01, ***P < 0.001)." (PMID 37418282, 2023). "Protein-protein interaction network analysis revealed that MRPS11 and MRPS12 were key genes, both of which were down-regulated in ischemic stroke." (PMID 37418282, 2023). "One potential application of MRPS11 and MRPS12 is as biomarkers for the diagnosis of ischemic stroke." (PMID 37418282, 2023). "The identification of MRPS11 and MRPS12 as potential markers in transcriptomic analysis of ischemic stroke highlights the importance of these genes in neurological disorders and their potential as therapeutic targets." (PMID 37418282, 2023). "Further research is needed to validate the robustness of MRPS11 and MRPS12 as markers for ischemic stroke diagnosis and as therapeutic targets." (PMID 37418282, 2023). "The Pseudo-time series analysis found that the expression of MRPS12 decreased gradually with the differentiation of pre-B cell CD34 cells in ischemic stroke, suggesting that the downregulation of MRPS12 expression may play an important role in ischemic stroke." (PMID 37418282, 2023). "Finally, in order to verify the expression of MRPS11 and MRPS12 in peripheral blood of patients with ischemic stroke, clinical samples were collected and PCR experiments were conducted." (PMID 37418282, 2023).
lung adenocarcinoma (1 paper, 2021). A carcinoma that arises from the lung and is characterized by the presence of malignant glandular epithelial cells. "Upregulation of MRPL22 (HR = 1.5, p = 0.0048), MRPL28 (HR = 1.5, p = 0.0098), MRPL21 (HR = 1.7, p = 0.001), MRPL12 (HR = 1.7, p = 0.00059), MRPS12 (HR = 1.6, p = 0.002), and MRPL17 (HR = 1.5, p = 0.0051) were correlated with poor overall survival in lung adenocarcinoma." (PMID 34925439, 2021). "The Cytoscape with cytoHubba tool kits, GEPIA, and c-BioPortal analysis suggested that upregulated hub genes of MRPL22, MRPL28, MRPL21, MRPL12, MRPS12, and MRPL17 are correlated with poor overall survival and may play a key role by cooperating with ALDOA in lung adenocarcinoma." (PMID 34925439, 2021).
Ménière disease (1 paper, 2014). "In a previous work, we sequenced the MRPS12 protein in 21 Ménière disease patients who suffered a chemical labyrinthectomy by using gentamycin." (PMID 25642242, 2014).
cancer (4 papers, 2019 to 2024). A tumor composed of atypical neoplastic, often pleomorphic cells that invade other tissues. "In particular, MRPS11 and MRPS12 have been implicated in the pathogenesis of cancer." (PMID 37418282, 2023). "Furthermore, there is compelling emerging evidence that increased MRPS12, MRPS16 and MRPS18B expression and association with metastatic capacity are observed across five different cancer types, collectively." (PMID 39354291, 2024). "MRPS12 and MRPS12 are known to be altered in many and different cancer types, which could explain their particularly different behavior." (PMID 30626316, 2019). "An upregulation of MRPS12 is observed in different types of cancer as opposed to non-tumor controls." (PMID 38259479, 2023).
tumour (3 papers, 2023 to 2024). "Given the known effect of tigecycline on MRPS12 expression, we suggest that studies assessing the interplay between tumour recurrence, tamoxifen resistance and MRPS12 expression is an ideal starting point." (PMID 39354291, 2024).
MRPS12 also shares sentences with these, for which no sentence is quoted: cholangiocarcinoma (1 paper); gastric cancer (1); lung carcinoma (1); neurological disorders (1); preeclampsia (1); Stroke (1).